MUC2 (mucin 2, oligomeric mucus/gel-forming)
Diseases named in the same sentence as MUC2 in open-access papers (continued):
Sharing a sentence is not in itself a finding about the gene and the disease.
tumor (continued). "Multiple types of cells were found within the tumor organoid in a heterogeneous manner, such as paneth cells expressing Lysozyme (Lysz) and epithelial cells expressing Villin 1 (Vill), while a lower abundance of Mucin2 (Muc2)-expressing goblet cells were observed in the tumor organoids." (PMID 38954022, 2024). "Furthermore, dendritic cells exposed to MUC2 produce less TNFα and IL-12, as well as more IL-10 and TGFβ1 in the large intestine, which suggests that MUC2 can deliver immunoregulatory signals to support tumor growth and treatment resistance." (PMID 34300195, 2021). "Dexamethasone also significantly reduced mucinous tumor mass in a PMP xenograft model, decreasing not only MUC2 content but also the number of tumor cells, suggesting that this drug in PMP might exert a dual role as inhibitor of mucin production and cell proliferation." (PMID 34885075, 2021). "In addition, Muc2 also has a function as a tumour suppressor." (PMID 23776483, 2013). "For the three PMP tumors (P8629, P8639 and P8605), MUC2 and AGR2 had intense staining among the epithelial tumor cells." (PMID 40018643, 2025). "In specific, study reported that tumor cells showed expression levels of MUC1 (77%), MUC2 (2%), MUC5B (63%), MUC5AC (36%) and MUC6 (21%)." (PMID 40655139, 2025). "Expression of secreted mucins MUC2, MUC5AC, and MUC6 was detected in the cytoplasm (94%, 59% and 12% of all tumours, respectively)." (PMID 39966658, 2025). "These tumours frequently retained positive staining for MUC-1, MUC-2, SATB2 and TFF-3, suggesting that these tumours maintain some degree of intestinal differentiation." (PMID 40935920, 2025). "Immunostaining of the tumor cells showed MUC5AC, MUC2, trypsin, and BCL1 negativity, leading to the diagnosis of intraductal tubulopapillary carcinoma." (PMID 41235002, 2025). "Immunohistochemistry of the tumor cells revealed positivity for MUC5AC and MUC6 and negativity for MUC2 and CDX2." (PMID 41256328, 2025). "In a particular study, the suppression of MUC2, the primary component of intestinal mucus, resulted in the phosphorylation of STAT3 in tumor cells via the cytokine IL-6." (PMID 38709264, 2024). "To investigate the role of CBPRS in the tumour microenvironment (TME) at the single-cell transcriptome level, we analysed the expression patterns of SOD1, MUC2, FKBP4, LOXL2, GPC1 and SNAI3 in different cell types." (PMID 38577594, 2024). "In contrast, in addition to Clu and Ly6a, the tumor stem cell population of BLM tumors had significant upregulation of differentiation-related genes such as Guca2a, Car1, Cdx2, Car2, and Muc2." (PMID 38893159, 2024). "In the tumor tissues, fibrinogen family (FGA/FGB/FGG), mucin 2 (MUC2), and transforming growth factor beta induced (TGFBI) proteins were ranked higher than other tissues." (PMID 39305996, 2024). "Immunohistochemical results of the perihilar tumor showed MUC1 (2 +), MUC2 (-) and MUC5AC (3 +), and the BilIN lesions exhibited MUC1 (-)." (PMID 37721561, 2023). "Tumours of the int group usually express cytokeratin-20 (CK20), caudal-type homeodomain transcription factor 2 (CDX2), and mucin-2 (MUC2)." (PMID 37504367, 2023). "The rate of CDX2 positive expression in the tumor sections with positive CD10 and MUC2 expression was significantly higher than that in sections with negative CD10 and MUC2 expression." (PMID 37602699, 2023). "Luminal eosinophilic secretions within CRC tumour glands stain differently to PAS, MUC1 and MUC2, suggesting differences in tumour biology." (PMID 34314467, 2021). "KLK6 mRNA was chosen because it is ectopically expressed in CRC tumor in contrast to CEACAM5 and MUC2 that are expressed at similar levels in CRC tumors and normal colon." (PMID 32049988, 2020).
tumor (continued). "In addition, MUC2 downregulation has been associated with increased expression of tumor-associated antigen carcinoembryonic antigen-related cell adhesion molecules 5 and 6 (CEACAM5 and CEACAM6), which are involved in cell adhesion, migration, tumor invasion, and metastasis." (PMID 29967641, 2018). "In total, we quantified approximately 4200 proteins and found that mucinous (e.g. MUC1 and MUC2) and mesenchymal proteins (such as THBS2, COL11A1, and CTHRC1) were significantly upregulated in the primary tumor compared to healthy surrounding tissue." (PMID 29901861, 2018). "We also observed LGR5−/MUC2+ cells with goblet‐like morphology intermingled between LGR5+ and LGR5− compartments throughout the tumor." (PMID 28468934, 2017). "One million SR control or MUC2 shRNA-expressing cells were implanted orthotopically in BALB/c mice, and macroscopic tumor nodules indicative of tumor formation were detected." (PMID 25322805, 2014). "For MUC2, the intestinal-type IPMN had a significantly higher U-index (P>0.001) compared to the other neoplasms, including gastric-type IPMN and PDAC, and the U-index for gastric-type IPMN was significantly lower (P = 0.002) than that for PDAC." (PMID 24714692, 2014). "To accurately quantify relatively MUC2 mRNA levels, we used a real-time PCR assay in 74 HCC and matched non-tumor tissues." (PMID 23347460, 2013). "We found that the frequency of MUC2 hypermethylation was 46 cases in HCC samples and 14 cases in non-tumor tissues." (PMID 23347460, 2013). "For sig-type GC, both the tumor lesion and background mucosa mostly showed strong expression of CTSE and MUC5AC, whereas expression of MUC2 was very weak in both of them." (PMID 23451082, 2013). "MUC2 expression was significantly difference between HCC tissues and matching non-tumor tissues (p < 0.0001)." (PMID 23347460, 2013). "This analysis showed down-regulated target gene (CXCL12, FABP1, MUC2 and PDCD4) expression in tumour compared to normal tissues, in keeping with their documented tumour suppressor functions, when using the larger set of samples." (PMID 20122155, 2010). "Tumor cells in our case expressed the apomucins MUC1 and MUC2 Several mucin genes designated MUC genes have been identified." (PMID 18768087, 2008). "We found that CEACAM1-S/L, CEACAM7-1/2, MUC2 and CK20 mRNAs were expressed at lower levels in the primary tumour compared to normal colon." (PMID 16755296, 2006). "The tumor cells and intraluminal mucin were diffusely expressed MUC1 and MUC5AC and only focally expressed MUC2." (PMID 15907218, 2005). "Taking into account the expression combinations of HGM, MUC6, MUC2 and CD10, the incidence of G-phenotype tumours was significantly higher in the peritoneal recurrence group than in the control group." (PMID 15354218, 2004). "Although the mRNA of MUC2 was expressed at constant levels in PAC120 and HID tumours, a variable expression of the MUC2 protein was observed." (PMID 14760390, 2004). "Such a discrepancy between mRNA and protein levels suggests that MUC2 expression is subject to differential post-transcriptional regulation in hormone-dependent (HD) and HID tumours." (PMID 14760390, 2004). "In contrast, goblet cell markers, such as KLF4, mucin 2 (MUC2), and SAM pointed domain-containing Ets transcription factor (SPDEF), were consistently downregulated in tumor tissue, aligning with the literature describing a reduced goblet cell population in the neoplastic intestinal epithelium." (PMID 41303610, 2025).
tumor (continued). "Notably, the silencing of MUC2 increases IL-6 secretion, which activates the STAT3 signaling pathway, promoting tumor cell migration, epithelial-mesenchymal transition (EMT), and metastasis." (PMID 41378310, 2025). "Moreover, the tumor number was positively correlated with FASN expression and Oil red O result, but was negatively correlated with MUC‐2 and ZO‐1 expression." (PMID 40433987, 2025). "One possible explanation includes the overexpression of mucin-2 (MUC-2) protein, which generally coats the intestinal epithelium and may inhibit antitumor effector immune responses, promoting tumor growth and progression." (PMID 41372917, 2025). "Interestingly, we showed that knocking down Cdx2 significantly reduced the expression of differentiated lineages-related genes such as Muc2, Atoh1, and Guca2a in BRAF mutant tumor-derived organoids." (PMID 38893159, 2024). "With this aim, we designed this retrospective study to demonstrate profiles of MUC expression (MUC1, MUC2, MUC5AC, and MUC6) of different histologic patterns within the same tumor among pulmonary adenocarcinomas and investigate correlations of MUC expression with clinicopathologic features." (PMID 36367122, 2023). "We designed this retrospective study to demonstrate profiles of MUC expression (MUC1, MUC2, MUC5AC, and MUC6) of different histologic patterns within the same tumor among pulmonary adenocarcinomas and investigate correlations of MUC expression with clinicopathologic features." (PMID 36367122, 2023). "Regarding tumor stage, cases with advanced depth of invasion (pT4) demonstrated a tendency towards a loss of MUC5AC and CDX2 but not MUC2." (PMID 37240039, 2023). "The variable expression patterns of MUC2 (i.e., marker for intestinal metaplasia) and MUC4 (i.e., marker for spasmolytic polypeptide expressing metaplasia (SPEM)) seen in the adjacent non-tumor tissues suggest the presence of metaplastic changes in these peritumoral sites." (PMID 37085819, 2023). "Immunohistochemically, the tumor cells were positive for intestinal markers, namely MUC2 and CD10, and negative for gastric markers, namely MUC5AC and MUC6." (PMID 35898822, 2022). "The expression levels of Ki-67 and EpCAM were retained in CRC PDOs, whereas MUC2, a differentiation marker, was not expressed in either the original tumor or PDOs." (PMID 35379798, 2022). "Tumor immunohistochemical analyses were presented as follows: Inhibin-α (-), ER (-), Vimentin (mesenchyme +), CK7 (+), CK19 (+), CK20 (−), CEA (−), MUC-1 (+), MUC-5AC (+), MUC-6 (+), MUC-2 (−), S-100p (focal+), and Ki-67 (12% +)." (PMID 33592896, 2021). "We hypothesize that the expression of PD-L1, GLUT-1, e-cadherin, MUC2, and CDX2, in addition to the MMR proteins in tumor samples, can help create an IHC biomarker panel that is able to discern patient prognosis in early-stage colon cancer." (PMID 34885019, 2021). "To further investigate the histopathological feature of tumor organoids and how this relates to parental tissues, we performed immunohistochemistry for pancreatic markers KRT7, MUC1 and MUC5AC, and the intestinal markers KRT20 and MUC2." (PMID 33327494, 2020). "The shMLL1 human Ls174T xenografts and sphere cells showed enhanced differentiation with an increase in the expression of the Paneth cell-specific genes DEFA5 and LYZ and the goblet cell markers MUC2 and ITF, as was also observed in the β-catGOF mouse tumor model." (PMID 33349639, 2020). "Of note, the three tumor lesions shared the same immunohistochemical staining pattern, showing negative expression of CK7 and CK20 markers and positive expression of CDX2, MUC1, MUC2, and MUC3." (PMID 31779681, 2019).
tumor (continued). "This study confirmed the expression of MUC5AC and MUC6, as well as negative expression of MUC1 and MUC2 throughout the tumour, with the final diagnosis indicating mucin producing HCC." (PMID 30875782, 2019). "It was reported that MUC5A, MUC2, CK20, c-erbB2 were completely positively expressed in tumor cells of UCGD, meanwhile, MUC1, CK7, 34βE12 could also be the markers helping distinguishing similar cells." (PMID 30926888, 2019). "CDX2 has been shown to support MUC2 in its tumor suppressor activity and is not usually expressed in PDAC." (PMID 29899320, 2018). "The results showed that a low level of MUC2 expression was associated with advanced TNM stage, lymph node metastasis, lymphatic invasion, tumor in the rectum versus the colon, and large tumor size." (PMID 29967641, 2018). "While the gel-forming MUC2 was abundant in normal epithelium, it was remarkably reduced or absent in the tumor (p = 0.0019)." (PMID 30115016, 2018). "While the role of MUC2 protein in appendiceal PMP remains unclear, we postulated that the unique mucinous phenotype likely contributes to its distinct tumor biology, clinical behavior and relative chemoresistance." (PMID 29290997, 2017). "In Muc2 IECs, the data document decreased expression of Aconitase 1 (Aco1), and concomitant elevation of Acly, thus, increasing ATP-citrate-lyase (ACL)-dependent production of acetyl-CoA important for the proliferation of tumor cells and lipogenesis." (PMID 29069719, 2017). "Secretory mucins (MUC2 and MUC6) and the mucus might also act as a barrier to cancerous extension and decrease the aggressiveness of the tumor biology." (PMID 27102151, 2016). "Primary pulmonary enteric adenocarcinoma (PEAC) is defined as a pulmonary adenocarcinoma with a predominant component (>50 %) of intestinal differentiation and with tumor cells positive for at least one intestinal marker such as caudal-related homeobox 2 (CDX2), CK20, or MUC2." (PMID 26677401, 2015). "CK7 and CK20 were both negative in our case, but positive CDX2 and MUC2 confirmed the tumor’s urachal origin." (PMID 23914849, 2013). "There was no binding to the insoluble mucins isolated from the tumor samples, which contain mainly MUC2 and no MUC5AC." (PMID 22563496, 2012). "No other significant associations between tumor location and MUC gene expression were detected, though expression of MUC2 in tumors in the lower end of the common bile duct trended toward worse survival than no MUC2 in tumors there (P = 0.061)." (PMID 22027009, 2011). "In morphologically determined pancreatobiliary-type adenocarcinomas (n = 67), most tumours (58 of 65) had diffuse CK7 expression (in >40% of the tumour cells) or were largely negative for MUC2 (62 of 65) and CDX2 (57 of 65)." (PMID 19236510, 2009). "According to the pattern of mucin expression, four tumors were classified as MUC2 positive indicating an intestinal type of tumor differentiation, while seven were MUC5AC positive tumors, indicating a gastric type of tumor differentiation." (PMID 19272137, 2009). "MUC2 was detected only in the tumour cell line, but not in the normal human pancreas and tumour samples." (PMID 14760381, 2004). "Our present results revealed that the incidences of HGM-positive tumours and MUC2-negative tumours were significantly higher in the peritoneal recurrence group than in the control group." (PMID 15354218, 2004). "Tumours were classified into gastric (G), gastric and intestinal mixed (GI), intestinal (I) or unclassified (UC) phenotypes according to the immunopositivity of HGM, MUC6, MUC2 and CD10 stainings." (PMID 15354218, 2004). "Besides MUC2 and MUC5AC, other mucins, such as MUC1, MUC4, and MUC6, may also be dysregulated in CRC and contribute to tumor progression." (PMID 39682117, 2024). "MUC2 expression was downregulated to 43% of CRC without correlation between tumor stage or site." (PMID 39337548, 2024).
tumor (continued). "In the present study, we first analyzed the tumor and adjacent non-tumor tissues of the GC patient cohorts and the biopsy tissues of the FD patients to measure the relative mRNA expression of gastric (MUC1, MUC5AC, MUC6) and intestinal (MUC2, MUC4, MUC13) mucins." (PMID 37085819, 2023). "Moreover, four out of four organoids derived from CRC with mucinous components showed intense and extended MUC2 staining, suggesting a good fit between the organoids and their originating tumor (not shown)." (PMID 36831331, 2023). "In the present study, we found that MUC2 was overexpressed in almost all MCAs; its expression was seen in the epithelial cells that comprise the MCAs as compared to the normal colon regardless of tumor location." (PMID 36916704, 2023). "Regarding the intestinal mucins, a significant increase in MUC13 mRNA expression was seen in the paired tumor tissues compared to the adjacent non-tumor and FD tissues whereas no significant alterations in expression were seen for MUC2 and MUC4 mRNA among the different sample types." (PMID 37085819, 2023). "Therefore, regarding MUC1, MUC2, MUC5AC, and MUC6, the most important point seems to be represented by the simultaneous and the correct use of all four of these mucins, and the integration of their expression pattern with tumor morphology." (PMID 35583805, 2022). "We observed high MUC2 expression (a marker of intestinal type gastric cancer) in JSC15-3 cells and high MUC5AC and MUC6 expression (markers of stomach type gastric cancer) in JSC17-7 cells, which are consistent with differentiation status of original tumour tissues." (PMID 31607750, 2019). "Large amounts of MUC2 in MCA endowed the tumor cells with higher malignancy than non-MCA." (PMID 29786668, 2018). "In particular, CK20, MUC2, MUC5AC, MUC6 and β-catenin showed disparate expression patterns that may in part be ascribed to clinicopathologic factors such as tumor location, mucinous components, differentiation, and MSI-status, conceivably reflecting diverse underlying genetic mechanism(s)." (PMID 28824332, 2017). "Immunohistochemical analyses revealed a similar expression and distribution patterns of CDX2 (nuclear), CK20 (cytoplasmic), E‐Cadherin (membrane), MUC2 (extracellular,; intracellular signet ring PMP) and MUC5AC (extra‐ and intracellular, and Z') in PMP PDX tumor as in human tumors." (PMID 26833741, 2016). "However, a sub-group of EPHB2-/ERBB3+ cancer cells were not positive for MUC2 in these tumours (white arrows)." (PMID 26367378, 2015). "Since the growth of the MUC2 shRNA transfectants was not altered in vitro, we hypothesized that the changes in tumor growth in vivo may result from altered tumor-microenvironment interaction." (PMID 25322805, 2014). "The tumor in our case was negative for MUC2, MUC4, MUC5AC and MUC6." (PMID 20550696, 2010). "The incidence of HGM-positive tumours and MUC2-negative tumours was significantly higher in tumours with peritoneal recurrence than in tumours without recurrence (73.3%, 44 out of 60 cases vs 54.3%, 63 out of 116 (P=0.022); and 70.0%, 42 out of 60 vs 38.8%, 45 out of 116 (P=0.0002), respectively)." (PMID 15354218, 2004). "MUC1 and MUC2 mucins were not simultaneously expressed in tumour cells." (PMID 14760390, 2004). "All tumours displayed a high and constant expression of MUC2 and no expression of MUC4 mRNA." (PMID 14760390, 2004). "Moreover, while KLK6 and SLC35D3 were CC-tumor specific in the sense that only CC tumor tissue expressed the biomarkers compared to normal colon tissue or normal colon epithelial cells, CEACAM5 and MUC2 were expressed at approximately the same levels in normal and cancerous colon tissues." (PMID 32049988, 2020). "The contradictory role of MUC2 as an inflammation suppressor and a promoter for tumor initiation in gastrointestinal tract cancers might suggest that gastrointestinal tract cancers originate from cells that express MUC2 rather than MUC2 itself as playing a role in the malignant process." (PMID 30922401, 2019).